AQP1 (aquaporin 1 (Colton blood group))
Diseases named in the same sentence as AQP1 in open-access papers (continued):
Sharing a sentence is not in itself a finding about the gene and the disease.
pulmonary edema (continued). "In the current study, different doses of TFENF were found to promote alveolar fluid transport by regulating AQP-1, AQP-5, αENaC, βENaC, and Na+-K+-ATPase to reduce pulmonary edema." (PMID 34887746, 2021). "The N. fordii water decoction promotes the expression of AQP-1 and AQP-5 in ALI and increases the clearance and transfer of lung water, improves water metabolism, and reduces pulmonary edema." (PMID 34887746, 2021). "Towne JE demonstrated that the expression levels of AQP-1 and AQP-5 decreased in lungs with pulmonary edema (PE) following viral infection." (PMID 28577538, 2017). "In this study, the low expression of AQP1 and AQP5 don’t successfully eliminate alveoli and interstitial water after SAP, therefore, which leads to the pulmonary edema and injury." (PMID 28577538, 2017). "In conclusion, our study shows that the expression of AQP1 increases in the pathological process of pulmonary edema induced by FES and that the altered expression is consistent with the severity of pulmonary edema." (PMID 27455237, 2016). "In this study, we investigated the association of AQP1 expression with the pathological features of pulmonary edema in FES mouse models and then demonstrated the potential mechanism of FFA-induced AQP1 regulation in pulmonary microvascular endothelial cells (PMVECs)." (PMID 27455237, 2016). "Our results demonstrate that AQP1 may play important roles in pulmonary edema induced by FES and can be regarded as a new therapy target for treatment of pulmonary edema induced by FES." (PMID 27455237, 2016). "In our study, these two kinds of AQP1 inhibitors relieved pulmonary edema, although they are not specific for AQP1 inhibition." (PMID 27455237, 2016). "In addition, recent studies demonstrated that the expression levels of AQP1 and AQP5 in the lung decreased in viral infection model of pulmonary edema." (PMID 23741323, 2013). "However, the roles of AQP1 and AQP4 expression in pulmonary edema remain controversial." (PMID 25705683, 2015).
astrocytomas (17 papers, 2002 to 2024). "Increased expression of AQP1 was seen in the Virchow–Robin region of astrocytoma wherein cancer cell penetration occurs, but expression is sparse in the necrotic core, proposing an association between AQP1 and tumour angiogenesis." (PMID 38336645, 2024). "AQP1-null mice caused impaired tumor angiogenesis and elevated AQP1 expression led to increased blood vessel formation in astrocytomas." (PMID 36010640, 2022). "Previous studies have shown that the expression of AQP1 is positively associated with invasion, angiogenesis, cell migration, and the formation of edema in malignant tumors, and high‐grade astrocytomas express higher levels of AQP1 than low‐grade astrocytomas." (PMID 32253832, 2020). "AQP1, expressed normally in the choroid plexus epithelium, was over-expressed and up-regulated in all types of glioblastoma and associated with the severity and grades of astrocytoma." (PMID 25886458, 2015). "Another study found that as astrocytoma progressed from low to high grade, the intensity of AQP1 expression increased significantly." (PMID 38336645, 2024). "In this case, AQP1 showed an increased number of transcripts in astrocytomas compared than in oligodendroglioma tumors (*p ≤ 0.05)." (PMID 38476871, 2024). "AQP5 has been indicated to be also involved in astrocytoma development, although compared to the prominently expressed AQP1 and AQP4, its expression is low." (PMID 36010640, 2022). "For example, although there was little AQP1 immunoreactivity in normal brain parenchyma, among astrocytomas, AQP1 was expressed in microvessel endothelia and neoplastic astrocytes." (PMID 35847914, 2022). "More importantly, we discovered that combination of AQP1 and β-catenin expression was an independent prognosis factor for astrocytoma patients and it was a better survival predictor than either AQP1 or β-catenin alone." (PMID 29245912, 2017). "Expression of AQP1 was also positively correlated with histological grade (rs = 0.163, P = 0.039) and high expression of AQP1 indicated worse outcome of astrocytoma patients." (PMID 29245912, 2017). "In conclusion, our study provided a novel more precise prognostication for predicting astrocytoma prognosis based on combinatorial analysis of AQP1 and β-catenin expression." (PMID 29245912, 2017). "In this study, we revealed the function of AQP1 in astrocytoma progression and provided the first clinical evidence that AQP1 expression was positively correlated with β-catenin." (PMID 29245912, 2017). "Then western blot analysis of AQP1 protein expression was performed using fresh frozen astrocytoma specimens." (PMID 29245912, 2017). "In the following studies, we conducted in vitro experiments to validate the function of AQP1 in astrocytoma." (PMID 29245912, 2017). "In the present study, we explored the relationship between AQP1 and β-catenin by clinical and cellular analyses and demonstrated for the first time that AQP1 expression was positively correlated with β-catenin in astrocytoma specimens." (PMID 29245912, 2017). "Up-regulation of AQP1 was shown in the perivascular area of astrocytoma where infiltration of tumour cells occur, in contrast to the scarce expression in the necrotic centre, suggesting a link between AQP1 and tumour angiogenesis." (PMID 28146084, 2017). "AQP1 in astrocytes has been detected in astrocytomas in subarachnoid hemorrhage tissue, in Creutzfeldt–Jakob disease (CJD), in bovine and murine spongiform encephalopathy, and in a rat epilepsy model." (PMID 27420057, 2016). "In low-grade astrocytomas, AQP1 immunoreactivity was present mostly in the plasma membrane, whereas in high-grade astrocytomas, massively-upregulated AQP1 was also distributed throughout the cytoplasm." (PMID 27420057, 2016). "In high-grade astrocytomas, AQP1 immunoreactivity was massively upregulated and distributed throughout the cytoplasm of neoplastic cells." (PMID 12237771, 2002).
astrocytomas (continued). "In low-grade astrocytomas, AQP1 immunoreactivity was present in tumour cells, mostly in the region of the cell membrane." (PMID 12237771, 2002). "The presence of AQP1 immunoreactivity in both cell membrane and cytoplasm of high-grade astrocytoma cells suggests a high turnover of AQP1 protein." (PMID 12237771, 2002). "However, Aqp1 was expressed in microvessel endothelia in human astrocytoma and metastatic carcinomas." (PMID 38474310, 2024). "AQP1 is also highly related to the migration and proliferation of astrocytoma." (PMID 36010640, 2022). "However, of note, the functional roles of AQP1 in astrocytoma progression are unclear due to limited research and a restriction of sample size." (PMID 29245912, 2017). "Next, we investigated clinical role of AQP1 by the same cohort of 160 astrocytoma specimens." (PMID 29245912, 2017). "In conclusion, combined AQP1 and β-catenin expression may be used as a powerful predictor of survival of astrocytoma patients." (PMID 29245912, 2017). "We also discovered the functional role of AQP1/β-catenin pathway in astrocytoma progression." (PMID 29245912, 2017). "Only endogenous AQP1 expression in astrocytoma tissues could be found by immunohistochemistry analysis and Western blot." (PMID 29245912, 2017). "AQP1 expression was predominantly confined to the membrane of a proportion of tumor cells in Grade II astrocytoma, while there was wider and denser membranous and intracytoplasmic expression in Grade III and Grade IV and AQP1 expression was higher in high-grade than of low-grade group (P = 0.009)." (PMID 29245912, 2017). "To further validate the relationship between AQP1 and β-catenin, combinatorial analysis of AQP1 and β-catenin was evaluated by the same cohort of 160 astrocytoma specimens and we demonstrated for the first time that AQP1 expression positively correlated with β-catenin (rs = 0.158, P = 0.045)." (PMID 29245912, 2017). "In addition, our results revealed that AQP1 and β-catenin could co-immunoprecipitate with each other in astrocytoma tissues and 3×Flag-AQP1/LN229 cells, respectively." (PMID 29245912, 2017). "Furthermore, we proved the functional role of AQP1/β-catenin pathway in astrocytoma progression." (PMID 29245912, 2017). "However, the role of AQP1 in astrocytoma progression has not been systematically analyzed and no any clinical evidence was provided about the association of AQP1 and β-catenin until present." (PMID 29245912, 2017). "Our results showed that AQP1 expression was too low to be detected in the control group, whereas it exhibited higher expression in both Grade III and Grade IV than Grade II astrocytoma specimens." (PMID 29245912, 2017). "Most importantly, we demonstrated for the first time that combined AQP1 and β-catenin expression was an independent prognosis factor for both OS and PFS of astrocytoma." (PMID 29245912, 2017). "For example, AQP1 and AQP4 were massively up-regulated in high-grade astrocytomas, as compared with low-grade ones and normal brain tissues." (PMID 25886458, 2015). "AQP1 expression was absent in the proliferating endothelium of Grade IV astrocytoma, whereas in perivascular areas, it exhibited a more clustered and denser distribution." (PMID 29245912, 2017). "Both univariate and multivariate Cox proportional hazard regression analysis demonstrated that combination of AQP1 and β-catenin expression was an independent factor for astrocytoma (OS: P = 0.048; PFS: P = 0.015) independent of age, tumor size and histological grade." (PMID 29245912, 2017).
osteosarcoma (17 papers, 2016 to 2024). A usually aggressive malignant bone-forming mesenchymal neoplasm, predominantly affecting adolescents and young adults. "RhoA expression was similarly reduced in two osteosarcoma cell lines, U2OS and MG63, following AQP1 down-regulation by shRNA, which was associated by a decrease in proliferation." (PMID 38336645, 2024). "Previous studies suggested that miR495-3p modulates the expression of aquaporin-1 (AQP1), a protein with a potential role in osteosarcoma and multiple myeloma development." (PMID 35645340, 2022). "VAMP8, A2M, HLA-DRA, SPARCL1, HLA-DQA1, APOC1 and AQP1 were identified continuously upregulating during the oncogenesis and metastasis of osteosarcoma." (PMID 32665038, 2020). "AQP1 can promote osteosarcoma cell proliferation, adhesion, invasion and tumorigenesis by targeting TGF-β signaling pathway and focal adhesion genes, and recruit human BM-MSCs into the osteosarcoma microenvironment." (PMID 32665038, 2020). "Down-regulation of Rho GTPases following by AQP-1 silence-suppressed tumorigenesis of osteosarcoma cells." (PMID 33209198, 2020). "Previous data has suggested that AQP1 plays a contributory role in the progression of osteosarcoma, multiple myeloma and rheumatoid arthritis through its effects on bone marrow mesenchymal stem cells and synovial tissue." (PMID 31700003, 2019). "Down-regulation of AQP1 expression with shRNA in two osteosarcoma cell lines U2OS and MG63 was accompanied by inhibition of proliferation." (PMID 28146084, 2017). "We found that AQP1 levels in osteosarcoma (OS) and hepatocellular carcinoma (HCC) cells were increased when tumor cells interacted with BM-MSCs in the microenvironment." (PMID 27409610, 2016). "In this study, we analyzed the involvement of AQP1 in osteosarcoma (OS) and hepatocellular carcinoma (HCC) progression due to BM-MSCs." (PMID 27409610, 2016). "Interestingly, aquaporin 1 (AQP1)—a water channel known to promote metastasis—was found to be increased significantly in osteosarcoma and hepatocellular carcinoma cells exposed to conditioned media from BM-MSCs." (PMID 31130595, 2019). "We evaluated whether conditioned medium from BM-MSCs (BM-MSC-CM) could affect the expression of the water channel AQP1 in osteosarcoma cells (U2OS) and hepatocellular carcinoma cells (SNU-398)." (PMID 27409610, 2016). "However, in osteosarcoma cells, downregulation of AQP1 leads to inhibited tumor cell proliferation." (PMID 38334883, 2024). "Our previous studies demonstrated the ability of medium conditioned from these stromal cells to increase aggressiveness of osteosarcoma and hepatocellular carcinoma cells through CXCR4 and AQP1." (PMID 36672233, 2023). "Moreover, AQP-1 could regulate cell apoptosis of osteosarcoma cells." (PMID 33209198, 2020). "TEA+ block of AQP1 water permeability reduced cell migration and invasion in in vitro models of osteosarcoma and hepatocellular carcinoma, with outcomes interpreted as consistent with action of TEA+ as a possible AQP1 inhibitor." (PMID 29922644, 2018). "Gene set enrichment analysis performed by Wu and colleagues indicated a positive correlation between AQP1 over-expression and TGF-β signalling pathway in osteosarcoma and expression of TGF-β1 and TGF-β2 was reduced in U2OP and MG63 cell lines when their AQP1 expression was down-regulated by shRNA." (PMID 28146084, 2017).
acute kidney injury (15 papers, 2019 to 2025). Sudden and sustained deterioration of the kidney function characterized by decreased glomerular filtration rate, increased serum creatinine or oliguria. "Research using a rat model revealed that mice with ischemia/reperfusion-induced acute kidney injury (AKI) had reduced levels of urine exosomal AQP-1 and AQP-2 protein and mRNA." (PMID 40305328, 2025). "This conclusion is supported by other analyses using an LPS-induced HK-2 cell model of septic acute kidney injury, which demonstrated that AQP1 plays a cytoprotective role." (PMID 39544938, 2024). "In rats with acute kidney injury, administration of vitamin D analogues can alleviate kidney injury, possibly by increasing the expression of AQP-1." (PMID 30809535, 2019). "In endotoxin-related acute kidney injury, mice with AQP1 knockout showed severe tubular injury histologically and functionally compared with wild-type mice, indicating a protective role of AQP1 in tubular injury and healing." (PMID 31572210, 2019). "Additionally, previous studies have shown that AQP1-null mice display increased tubular injury compared to wild-type mice following ischemia–reperfusion and endotoxin-related acute kidney injury, indicating a role of AQP1 in tubular injury and healing." (PMID 38542420, 2024). "Moreover, in acute kidney injury (AKI), fetuin-A and AQP1 + EVs may be used as diagnostic biomarkers." (PMID 37566042, 2023). "Similarly, another study supported that AQP1 suppressed M2 polarization under normal conditions, promoted M2 polarization after stimulation of LPS, and alleviated acute kidney injury by PI3K-induced macrophage M2 polarization." (PMID 34708074, 2021). "AQP1 plays a role in the protection against LPS-induced acute kidney injury (AKI) by promoting M2 macrophage polarization, which involves PI3K activation." (PMID 39544938, 2024). "For example, the aquaporin-1 (AQP1) protein level in urinary exosomes has been identified as a potential biomarker for acute kidney injury (AKI)." (PMID 32429335, 2020). "Thus, the polyuria in AQP1-KO mice does not appear to protect against endotoxemia-induced acute kidney injury but rather absence of AQP1 predisposed to enhanced endotoxemic renal injury." (PMID 31023968, 2019). "Thus, AQP1-facilitated cell migration and cell proliferation may be important for the structural and functional regeneration of tubules after acute kidney injury." (PMID 31023968, 2019). "Furthermore, the expression of fetuin–A is shown to be significantly upregulated, whereas aquaporin 1 (AQP1) is downregulated in the urinary EVs of acute kidney injury (AKI) patients, and hence, fetuin–A+ and AQP1+ EVs are considered biomarkers for AKI." (PMID 37835573, 2023). "AQP3, on the other hand, modulates inflammation through the Toll-like receptor 4 (TLR4) pathway, while AQP1 plays a role in immune responses by activating the PI3K pathway, promoting macrophage polarization, and protecting against lipopolysaccharide (LPS)-induced acute kidney injury (AKI)." (PMID 39544938, 2024).